STAT3 (signal transducer and activator of transcription 3)
Diseases named in the same sentence as STAT3 in open-access papers (continued):
Sharing a sentence is not in itself a finding about the gene and the disease.
cancer (continued). "We and others have previously demonstrated that STAT3 overexpression is an early event in HNSCC carcinogenesis, where STAT3 is upregulated and constitutively activated in cancer patients relative to healthy controls." (PMID 27855189, 2016). "It is known that BCPO alters several key pathways for cancer development, such as mitogen‐activated protein kinase (MAPK), PI3K/AKT/mTOR/S6K1 and STAT3 pathways." (PMID 27696789, 2016). "Pharmacologically targeting activated STAT3 and/or STAT5 has been an active area of cancer research." (PMID 27513743, 2016). "Furthermore, the translational relevance of these findings was assessed from the standpoint of generating a signature based on the expression and/or activation status of Rac1, Bcl-2 and STAT3, which could have implications for stratifying cancers by disease severity and chemoresistance." (PMID 26430964, 2015). "Several signaling pathways, including the STAT3, MAPK, and PI3K pathways, have been shown to regulate PD-L1 expression on cancer cells." (PMID 25889536, 2015). "Signal transducer and activator of transcription 3 (STAT3) has received considerable attention as a key inhibitor of inflammation and cancer." (PMID 26417930, 2015). "As important signaling molecules, JAK/STAT3 and ERK are deregulated in various types of cancer cell and can phosphorylate a series of transcription factors, which regulate gene expression and are important in cell proliferation, differentiation and survival." (PMID 25373392, 2015). "STAT3 is activated in EGFR wild-type NSCLC and correlates with cancer progression, including cell survival, migration and invasion." (PMID 25955608, 2015). "Weissmann and colleagues found that pSTAT3 is elevated in the cancer stem cell population in UBC specimens, suggesting that activation of STAT3 plays a role in the maintenance of cancer cell stemness." (PMID 25849286, 2015). "To further understand the effect of tocilizumab in the cancer stem cell fraction, we performed in vitro experiments with UM-HMC-3B cells treated with tocilizumab or with Stattic, a small molecule inhibitor of STAT3." (PMID 26287605, 2015). "Studies have confirmed that inflammatory activate immune cells product cytokines, such as NF- κB, STAT3, AP-1, FOXP3 and interleukin, which can stimulate cancer cell proliferation and survival." (PMID 25956656, 2015). "However, STAT3 inhibitor could not distinguish the STAT3 in normal cells and cancer cells and might cause severe side effects." (PMID 26474285, 2015). "Inhibition of HSP90 activity in cancer cells results in degradation of client proteins, such as TYK2 and RIPK1, and reduction in NF-κB signaling, STAT3 phosphorylation and ERK activation, the changes seen in DLBCL cells treated with doxycycline." (PMID 26142707, 2015). "To identify what downstream signals in cancer cells respond to IL-6, we looked at JAK2/STAT3 pathway." (PMID 25797257, 2015). "Whereas our study showed that in ESCC, SOX2 exerted a regulatory action upstream of STAT3/HIF-1α, another report indicated the action of SOX2 downstream of HIF-1α in cancer cells other than ESCC." (PMID 26370982, 2015). "They observed that paclitaxel treatment enhanced the expression of cancer stem cell-like markers in surviving cancer cells in vivo and coincided with significant activation of the JAK2/STAT3 pathway." (PMID 26442217, 2015). "Accumulating evidence suggests that STAT3 is one of the major transcription activators of VEGF and contributes to cancer invasion and metastasis via regulation expression of VEGF." (PMID 26783521, 2015). "STAT3 is also involved in IL-6-induced proliferation of RCC cells and in the activation of RCC cancer cells mediated by macrophages, thus representing an emerging target for the treatment of RCC." (PMID 28031890, 2015). "The results indicated that RKIP inhibited ERK, NF-κB, and Stat3 signaling, and activated GSK-3β signaling in NPC cells, which is consistent with the previous reports in the other types of cancers." (PMID 25915430, 2015).
cancer (continued). "However, since STAT3 deletion leads to decreased mitochondrial function and increased oxidative stress, a selective inhibition of its nuclear functions preserving mitochondrial activity may be beneficial in treating Y-P STAT3-driven cancer/drug resistance." (PMID 26106584, 2015). "Compared with the control group, lipopolysaccharide (LPS) induced phosphorylation of STAT3 at both Tyr705 and Ser727 in SGC7901 cancer cells." (PMID 26417930, 2015). "Of human cancer, there is a high frequency of activation of STAT1, STAT3 and STAT5, with a higher incidence of abnormal STAT3 activation in most tumors studied." (PMID 26464811, 2015). "DU145R80 show a cancer stem cell (CSC)-like signature with a high expression of CSC markers including CD44, CD133, NANOG, Snail, Oct4 and ALDH7A1 and CSC-related genes as STAT3." (PMID 26312765, 2015). "LIF-activated dermal fibroblasts gain cellular contractility and provide ECM remodeling via a crosstalk between the JAK1/STAT3 and RhoA/ROCK/MLC2 signaling pathways, reciprocally resulting in cancer cell invasion in vitro and in vivo." (PMID 25853091, 2015). "Of the seven members of the STAT protein family, STAT1, STAT3 and STAT5 have been demonstrated to be the most important for chronic inflammation and cancer progression." (PMID 26501341, 2015). "STAT3, a member of the JAK/STAT family of proteins, is the most promising new target for cancer therapy." (PMID 26580615, 2015). "Therefore, defining new therapeutic targets that antagonize STAT3 signaling is crucial for further understanding the regulation of this signaling pathway and the development of novel therapeutic strategies to inhibit prolonged activation of this pathway in human cancer." (PMID 26417930, 2015). "We also show that products secreted from CM prepared from mouse VAT promote mitochondrial dysfunction of cancer cells, and that this effect is mediated by the c-Jun N-terminal kinase (JNK)/STAT-3-signaling pathway." (PMID 26472027, 2015). "This is a result of the concerted expression of genes related to cancer stem cell maintenance through NF-κB/RELA and STAT3 as downstream mediators of TLR9 signaling." (PMID 26046794, 2015). "The low expression level of miR-20a, a negative regulator of STAT3, can enhance de-repressed STAT3 expression and activation and boost proliferation pathways in hepatocellular and this suggest miR-20a may represent a novel potential therapeutic target and biomarker for survival of cancer patients." (PMID 26631279, 2015). "Some of them, such as UBE2C, CASP3, CCND1/2, STAT3, JAK2 and MMP-9, have been used as markers of cancer malignancy." (PMID 26603105, 2015). "The specific inhibition of STAT3 is important for treating cancer cells because certain growth suppressive cytokines, such as IFN-γ, activates STAT1, which mediates growth suppressive signals, as well as STAT3, which promotes cell growth." (PMID 26010889, 2015). "Members of the miR-17–92 cluster targeted numerous cancer suppressor genes, e.g. Pten, BIM, E2F1, p21 and STAT3, showing functions in differentiation and apoptosis." (PMID 25647305, 2015). "Other proteins that are dysregulated in cancer are also affected by AIMs, including: JNK; JAK1 and STAT3; Her2 (ERBB2); death receptor 5 (TNFRSF10B); and cFLIP (CFLAR)." (PMID 25897966, 2015). "Inhibition of STAT-3 and telomerase; down-regulation of Akt and MEK; anti-cancer; induces autophagy." (PMID 24833337, 2014). "Second, STAT3 is known to increase the expression of various matrix metalloproteinases (MMPs), including MMP-1, MMP-2, MMP-7 and MMP-9, which facilitate cancer cell invasiveness by degrading various extracellular matrix proteins." (PMID 24995504, 2014).
cancer (continued). "NUR77 is frequently elevated in cancers and NRIP1 promotes mitogenic signalling in the developing mammary gland, while SMAD3 and STAT3 are known to be fundamental mediators of growth factor and cytokine signalling." (PMID 25261374, 2014). "FN-β1 integrin signal was also found to synergistically enhance STAT3 activation induced by EGF and IL-6 in breast or other cancer cells." (PMID 25327561, 2014). "Given that ginseng was reported to repress STAT3 activation in cancer cells, it is plausible to assume that RGE can suppress Th17 by inhibiting STAT3 phosphorylation, enhancing enhanced Treg cells by reciprocal regulation." (PMID 25147435, 2014). "Taken together, these data suggest that STAT3 activity mediates constitutive IDO expression and activity in human cancer cells." (PMID 24657910, 2014). "C1QTNF4 is an inflammatory cytokine capable of activating both Stat3/IL6 and NF-κB pathways, as shown in cancer cells." (PMID 24743338, 2014). "We find significant evidence of the OVOL, AP1, STAT1, STAT3, and NFKB1 TFs having important roles in MET, and more broadly in cancer." (PMID 24612742, 2014). "The mechanism is by apoptosis, since ST3-H2A2, a synthetic compound, binds to STAT3 N-terminal domain and activates expression of proapoptotic genes such as C/EBP-homologous protein (CHOP) to initiate apoptotic death in cancer cells." (PMID 24743778, 2014). "In mammals, the cytokine interleukin-6 and its downstream effector STAT3, a homologous pathway of the Drosophila Upds/JAK/STAT signalling, are involved in inducing intestinal inflammation and cancer." (PMID 24586740, 2014). "Second, we demonstrated that 17-AAG effectively blunted the IMQ induced STAT3 phosphorylation and HIF-1α protein accumulation in cancer cell lines." (PMID 24658058, 2014). "STAT3 signaling in MDSC can be modulated by IL-6, which has been shown to enhance CSCs and EMT in cancer." (PMID 24652403, 2014). "The functional link between these pathways is significant for the understanding of the PI3K- and STAT3-driven oncogenic mechanisms and identifies the TEC kinase, BMX, as a new cancer target." (PMID 24520283, 2014). "Testing combined treatments of STAT3 inhibitor and Herceptin resulted in a significant inhibition of growth for HER2-overexpressing cancer cells." (PMID 24297508, 2014). "Several studies have documented that aberrant activation of the STAT-3 signaling pathway contributes to neoplastic transformation in various malignancies, and have validated STAT-3 as a promising target for cancer therapy." (PMID 25296162, 2014). "The initial proteomic analysis indicated that among some of the major signaling pathways known to be key in cancer cells, activated STAT1 and STAT3, were differentially expressed and therefore potentially interesting signaling candidates in resistant cells." (PMID 24728078, 2014). "PGE2 released by cancer cells upregulates IDO expression in fibroblasts through an EP4/signal transducer and activator of transcription 3 (STAT3)-dependent pathway." (PMID 25060643, 2014). "Sesquiterpene lactones have anti-apoptotic activity in various cancer cell lines, and function via GSH depletion and inhibition of STAT3 activation." (PMID 25226283, 2014). "Based on our results, we concluded that IMQ activates the STAT3 and PI3K/Akt pathways to increase HIF-1α expression at both the transcriptional and translational levels in TLR7/8-negative cancer cells." (PMID 24658058, 2014). "Its combined roles in growth control, cancer stem cell (CSC) maintenance and radioresistance have lent growing credence to the therapy-sensitizing potential of STAT3 inhibition." (PMID 25268165, 2014). "Moreover, MDSCs (that have activated STAT3) may also increase STAT3 activity in cancer cells." (PMID 25075523, 2014). "For this gene set, we found significant enrichment of annotation for BC, PC, cancer, and MET, as well as regulation of gene expression by AP1, STAT1, STAT3, and NFKB1." (PMID 24612742, 2014).
cancer (continued). "The JAK2/STAT3 pathway is critical for cytokine and growth factor-mediated responses regulating EMT biology in fibrogenesis and cancer." (PMID 25405202, 2014). "Another line of evidence suggests that STAT3 negatively regulates CXCL10 expression, whose expression significantly enhances natural killer cell cytotoxicity for cancer cells." (PMID 24743778, 2014). "Therefore, silencing STAT3 by siRNA, curcumin and Stattic, and targeting miR-21 by antisense or small-molecule compounds may represent a potential therapeutic strategy for targeted treatment of cervical and other cancers which invariably overexpress STAT3." (PMID 25539644, 2014). "Several STAT3 and JAK2 inhibitors have been described and shown to inhibit the growth of various cancers that exhibit STAT3 activation." (PMID 25132836, 2014). "Activation of signal transducer and activator of transcription 3 (STAT3) is common in human cancers including NPC and plays an important role in the pathogenesis and progression of human cancers." (PMID 23658720, 2013). "Proteins involved in migration and invasion of cancer cells, like matrix metalloproteinases (MMP-1, MMP-2, MMP-10, etc.)and Twist, were regulated by STAT3 activation." (PMID 23704931, 2013). "As hTERT shRNA-mediated gene silencing down-regulated cancer stem cell marker CD44 and inhibited STAT3 phosphorylation, we next examined invasiveness properties of the hTERT knocked-down cells." (PMID 24386318, 2013). "Aberrations of STAT3 signaling in various cancer models were appreciated before STAT5, therefore investigators initially concentrated on targeting STAT3." (PMID 24308725, 2013). "Our study delineates the signaling pathway where STAT3 functions as a modulator for CD44 and hTERT, promoting a cancer stem cell phenotype." (PMID 24386318, 2013). "In the absence of doxorubicin, stable expression of a constitutively active form of STAT3 (STAT3C) prevented the modest imatinib-mediated activation of caspase-3/7, indicating that imatinib prevents cancer cell survival by inhibiting activation of STAT3." (PMID 23383209, 2013). "Apart from IL8, the co-regulation between NF-κB and AP1, CEBPB or STAT3 for genes IL1B, ICAM1, IL6, PTGS2, and SAA1 in the TF regulatory networks is consistent with previous observation in HNSCC or other cancer cells." (PMID 24069219, 2013). "This miRNA can be activated by STAT3 via PTEN and cyclin D and is part of an epigenetic switch linking inflammation to cancer." (PMID 24265725, 2013). "Specific ODN has been studied for STAT3 and STAT5 inhibition in various cancer cell lines including K562, U251, A172, A549, and SW480 in vitro and in mice xenograft model of Lung cancer." (PMID 24308725, 2013). "We previously found that STAT3 was constitutively activated in PDAC and it plays a role in the maintenance of a cancer stem cell phenotype." (PMID 24025152, 2013). "In human cancer cells, a constitutive activation of MAPK, STAT3, β-catenin, and various other signaling pathways triggers multiple immunosuppressive cascades." (PMID 23755373, 2013). "Our in vitro studies show that DPDIM exerts apoptotic effect by negatively regulating the activity of EGFR and its downstream molecules like STAT3, AKT and ERK1/2 which are involved in the proliferation and survival of these cancer cells." (PMID 23555785, 2013). "Signal Transducer and Activator of Transcription 3 (STAT3) belongs to the STAT family of transcription factors and affects expression of cancer-related genes." (PMID 24133496, 2013). "Recent data indicate the Signal Transducer and Activator of Transcription 3 (STAT3) pathway is required for VEGF production and angiogenesis in various types of cancers." (PMID 22530037, 2012).
cancer (continued). "Out of 17 cancer cell lines, figitumumab effectively inhibited the growth of three cell lines (SNU719, HepG2, and SNU368), decreased p-AKT and p-STAT3 levels, and induced G 1 arrest in a dose-dependent manner." (PMID 22438913, 2012). "In cancer, for instance, a number of oncogenic transcription factors such as activator protein 1 (AP-1), nuclear factor κB (NFκB), and signal transducer and activator of transcription (STAT)-3/STAT5 are constitutively expressed and thus may present promising targets for cancer prevention." (PMID 23905066, 2012). "Furthermore, PP may interact with gene associated with retinoid-interferon-induced mortality 19 (GRIM-19), a component of the mitochondrial electron-transport chain complex I that inhibits STAT3 to induce pro-apoptotic gene expression and thereby apoptosis of cancer cells." (PMID 23061049, 2012). "We found that, as a consequence of the EGFR inhibition, CL4 strongly inhibits the anti-apoptotic STAT3 and induces cell death selectively in EGFR-positive cancer cells by activation of caspase-3, caspase-8 and PARP." (PMID 21915281, 2011). "NSC74859 is a specific inhibitor of signal transducer and activator of transcription 3 (STAT3) activation and it decreases CD133-positive cells with suppression of cancer development." (PMID 22187659, 2011). "In cancer, by contrast, STAT proteins, particularly STAT3 and STAT5, become activated constitutively, thereby driving the malignant phenotype of cancer cells." (PMID 21680956, 2011). "Since STAT3 activation is important in the development of human cancers, including MM, and cladribine was able to inhibit STAT3 in MM cells, we hypothesized that the combinations of cladribine and a specific STAT3 inhibitor might exhibit super activity in inducing apoptosis in MM cells." (PMID 21679466, 2011). "Efforts have been made in developing small molecule inhibitors of STAT3 and JAK for cancer therapy and some of them showed good in vitro and in vivo antitumor activities." (PMID 22174819, 2011). "Signal transducer and activator of transcription 3 (STAT3) is one of STAT protein family and constitutively active in a wide range of human cancer cells." (PMID 21731766, 2011). "This is most probably due to the hyperactivation of STAT3 and/or decreased SOCS expression mediated silencing of cytokine and chemokine production in the context of other types of cancer cells." (PMID 21079774, 2010). "In our study, however, knocking-down Stat3 with Stat3 siRNAs resulted in a decrease in IL-6 expression in AS2 cells and two drug resistant cancer cell lines (KB-CPT100 and MCF-7/ADR)." (PMID 21122157, 2010). "Recent studies showed that mir-21 is a key determinant in IL-11/STAT3 anti-apoptotic signaling pathway and STAT3 activation of miR-21 and miR-181b-1 via PTEN and cylindromatosis (CYLD) are part of the epigenetic switch linking inflammation to cancer." (PMID 21461395, 2010). "Several oncogenic signaling pathways in cancer stem cells of HCC, have been described including activated PI3K/AKT, signal transducer and activator of transcription 3 (STAT3), Notch, Hedgehog, and transforming growth factor-beta (TGF-β)." (PMID 21331379, 2010). "Forty five (n = 45) cancer biopsies with confirmed histopathology and HPV16 positivity were re-evaluated for STAT3 and pSTAT3 expression." (PMID 20977777, 2010). "Although VEGF is upregulated in response to many inducers activated in cancer, only two major transcription factors have been identified for its promoter, hypoxia inducible factor (HIF)-1 and Stat3." (PMID 20204067, 2010). "We chose STAT3, which is phosphorylated by JAKs on Y705, as its persistent activation is the most common STAT form found in human cancers." (PMID 20149240, 2010). "To confirm that Stat3 regulated IL-6 expression in cancer cells, we transiently transfected AS2 cells with Stat3 siRNA to knock-down the expression of Stat3." (PMID 21122157, 2010).